SMAD3 (SMAD family member 3)
Diseases named in the same sentence as SMAD3 in open-access papers (continued):
Sharing a sentence is not in itself a finding about the gene and the disease.
liver fibrosis (continued). "The exosomes of WJ-MSCs can inhibit the TGFβ/Smad3 signaling pathway preventing further activation of HSCs and progression of liver fibrosis." (PMID 37275763, 2023). "In summary, FA has protective and antioxidant effects on TAA-induced hepatic fibrosis in rats by inhibiting the TGF-β1/Smad3 signalling pathway and differentially regulating the expression of microRNAs (miR-200, miR-30 and miR-21) in the liver." (PMID 37324465, 2023). "In our study, we discovered that AKF-PD decreased the protein expression of TGF-β1, p-Smad2 and p-Smad3 in the CCl4-induced rat liver fibrosis model." (PMID 37790613, 2023). "In a previous study, SMAD3 knockout mice had a lower degree of liver fibrosis induction than wild-type mice." (PMID 37446187, 2023). "On the other hand, miR-34 expression regulates the decapentaplegic homolog 3 (Smad3) pathway and is associated with the onset and progression of TGF-β1-induced liver fibrosis." (PMID 37833930, 2023). "As liver fibrosis is closely connected to liver cancer, the pathogenic roles of SMAD2 and SMAD3 were further explored in liver cancer in TCGA." (PMID 37790613, 2023). "Our study provided some implications about how liver fibrosis was connected with liver cancer by SMAD2/SMAD3 and autophagy." (PMID 37790613, 2023). "The main purpose of this research was to investigate the effects of exosomes of WJ-MSC on NOX gene expression levels and phosphorylation of Smad3 protein in TGF-β-induced liver fibrosis." (PMID 36544529, 2022). "TGF-β1 modulate liver fibrosis by activating Smad2 and Smad3 pathway, whereas Smad7 is known as an inhibitor of TGF-β112." (PMID 36482069, 2022). "Other studies have shown that the severity of liver fibrosis is associated with the expression of NOX enzymes in HSCs, which is related to the TGF-β/SMAD3 signaling pathway." (PMID 36544529, 2022). "Upon TGF stimulation, Smad3 is activated by phosphorylation and translocate to the nucleus, where it activates a fibrotic signaling pathway that leads to liver fibrosis." (PMID 36232933, 2022). "In an experimental model of liver fibrosis, PIAS4 silencing blocked recruitment of SMAD3, decreasing pro-fibrotic gene expression and ameliorating hepatic fibrosis." (PMID 35066606, 2022). "Another research showed that deltamethrin caused liver fibrosis through inhibition of Nrf2 expression and boost of NF-κB/TNF-α and TGF-β1/Smad3 pathway." (PMID 35126808, 2022). "Our results concur with previous studies, where they established a correlation between activation of TGF-β1/SMAD3 pathway and fibrogenesis in different animal models of hepatic fibrosis." (PMID 35625467, 2022). "In line with the recent study, we found that the TGF-β/Smad3 signaling pathway was involved in the protection of DIM against liver fibrosis." (PMID 36232707, 2022). "Inhibition of SMAD3 decreased collagen I expression while Smad2 increased collagen I expression, and Smad4 is crucial in liver fibrosis by supporting SMAD3 activity." (PMID 36482069, 2022). "Recent studies demonstrated that in a rat model of carbon tetrachloride-induced liver fibrosis, the expression of p-Smad2 and p-Smad3 in the liver was significantly increased." (PMID 36474240, 2022). "Taken together, these results suggest that Ufbp1, which lies upstream of Smad2/3, regulates liver fibrosis through Smad3 activation predominately." (PMID 34307359, 2021). "TGF-β promotes liver fibrosis and hepatocellular apoptosis through activation of Sma- and Mad-related protein 3 (Smad3) as a major TGF-β -signaling molecule." (PMID 33746950, 2021). "Zhong and colleagues' results indicated that Sirt6 alleviates EMT and liver fibrosis in hepatic stellate cells by deacetylating conserved lysine residues (K333 and K378) on Smad3." (PMID 34122724, 2021). "The expression levels of TGF-β1 and Smad3 were decreased in a carbon tetrachloride-induced liver fibrosis model in rats treated with the herbal decoction JinSanE, and Smad7 expression was found to increase." (PMID 33981353, 2021).
liver fibrosis (continued). "Many previous studies have shown that TGF-β-mediated activation of Smad3 pathway plays a critical role during the process of liver fibrosis." (PMID 33396939, 2020). "The present studies showed the influences of SREBP1c on both receptors for TGFβ1 and PDGFβ, the most important cytokines for inducing HSC activation and liver fibrosis, and on their downstream signalling pathways of Smad3 and Akt1/2/3 in HSCs." (PMID 32678475, 2020). "Increased liver fibrosis was accompanied by increased phosphorylation and nuclear localization of Smad3." (PMID 33396939, 2020). "Although both Smad2 and Smad3 are strongly activated in liver fibrosis, Smad3 appears to be the key element in the signal transduction pathways that are responsible for fibrosis." (PMID 32508821, 2020). "Phosphorylated Smad2 (p‐Smad2) and phosphorylated Smad3 (p‐Smad3) generated by TGF‐β1 lead to the activation of hepatic fibrosis." (PMID 32233073, 2020). "Based on the consistent expression of total Smad2 and Smad3, levels of TGF-β1 and phosphorylated Smad2 and Smad3 were upregulated in the liver fibrosis model, but decreased in the drug group, and the differences were statistically significant." (PMID 33488687, 2020). "Klf10 KO mice developed hepatic fibrosis due to the induction of ER stress, inflammation, and Smad3 signaling in a lipogenic condition induced by a high-sucrose diet (HSD)." (PMID 33396939, 2020). "Glycyrrhizin inhibited pro-fibrotic cytokine TGF-β1-mediated pathways, including Smad2, Smad3 as an active ingredient in astragalus saponins, changed the pathological morphology and prevented the liver fibrosis induced by the bile duct ligation (BDL) model." (PMID 32117622, 2020). "The downstream proteins, namely Smad2 and Smad3, are activated by phosphorylation, which further promotes the transcription of genes encoding ECM components, then accelerates the development of liver fibrosis." (PMID 32943114, 2020). "TGF-β1, a member of the pleiotropic cytokine family, plays a leading role in the development of liver fibrosis and improves extracellular matrix production, and can activate Smad3 to accelerate fibrosis progression." (PMID 31575049, 2019). "ECAD antagonize the profibrogenic TGF-β1 pathway by decreasing Smad3/2 phosphorylation, whereas loss of ECAD promotes the up-regulation of TGF-β1 and its target genes and facilitates liver fibrosis." (PMID 31695785, 2019). "Mechanistically, metformin suppresses TGF-β/SMAD3 signaling, thus mediating the antifibrotic effects in the CCl4 model of liver fibrosis in mice." (PMID 31718044, 2019). "The results demonstrated that IH improved liver fibrosis through downregulating TGF-β1 mediation of Smad3 and p38 MAPK signaling." (PMID 31467486, 2019). "Ecm1-KO mice spontaneously developed severe liver fibrosis with tremendous TGF-β/Smad3 and subsequent HSC activation." (PMID 31718044, 2019). "In hepatic stellate cells, TGFβ induces VDR binding to genes co-regulated by SMAD3, resulting in reduction of SMAD3-occupied liver fibrosis genes." (PMID 30678273, 2019). "The results presented here demonstrate that clusterin reduces hepatic fibrosis by inhibiting the activation of HSCs and the Smad3 pathway." (PMID 31739636, 2019). "It has been reported that metformin can mitigate carbon tetrachloride-induced TGF-β1/Smad3 signaling and liver fibrosis in vivo." (PMID 31011335, 2019). "Phosphorylation of Smad3 and its subsequent nuclear translocation are critical steps in the signaling cascade leading to hepatic fibrosis." (PMID 31739636, 2019). "The therapeutic mechanism of IH in liver fibrosis involves downregulating the TGF-β1/Smad3 and TGF-β1/p38 MAPK pathways." (PMID 31467486, 2019). "Group 3 (MPOE-treated) showed a sustained reduction of TGF-β1 and SMAD3 protein expression compared to the liver fibrosis control group (resp)." (PMID 29849890, 2018). "TGF-β1 and SMAD3 protein expression were significantly increased in the liver fibrosis control group than in the normal control." (PMID 29849890, 2018).
liver fibrosis (continued). "It is widely acknowledged that TGF-β1 is the most potent cytokine fostering hepatic fibrosis; through Smad2 and Smad3 phosphorylation, it activates HSCs to produce collagen III and FN." (PMID 29402324, 2018). "The molecular consequences of p-SMAD3 and TGFβR2 proteins and development of liver fibrosis were demonstrated that Stat3 is essential to collaborate with SMAD3 mediating TGFβ induced fibrotic response in hepatic stellate cells." (PMID 30346985, 2018). "The abrogation of TGF-β1 signaling through both Smad2 and Smad3 has been verified to be able to decrease liver fibrosis." (PMID 29743985, 2018). "Our study demonstrated that Cpd861 can attenuate hepatic fibrosis and its effects on liver function by decreasing Smad2 and Smad3 protein levels while increasing SnoN protein levels." (PMID 29402324, 2018). "The inhibition of TGF-β1 through both Smad2 and Smad3 significantly ameliorated liver fibrosis in several fibrotic animal models." (PMID 29743985, 2018). "Taken together, these findings indicates that downregulation of TGF-β1/SMAD3 signaling is a potential mechanism by which ADSC transplantation ameliorates liver fibrosis of T2D." (PMID 29258603, 2017). "Ginseng extract had an anti‐fibrosis effect in a CCl4‐induced liver fibrosis model by regulating the TGF‐β1/Smad signaling pathway via the inhibition of Smad3, Smad2, and TGF‐β1 expression." (PMID 28086769, 2017). "Here the authors show that ERG balances TGFβ signalling through the SMAD1 and SMAD3 pathways, protecting the endothelium from endothelial-to-mesenchymal transition and consequent liver fibrosis in mice via a SMAD3-dependent mechanism." (PMID 29026072, 2017). "Expression of phospho-Smad3 and its subsequent nuclear translocation are critical steps in the signaling cascade that results in hepatic fibrosis." (PMID 29152065, 2017). "PIAS4 promotes HSC activation and liver fibrosis by stimulating SMAD3 acetylation and target binding in a SIRT1-dependent manner." (PMID 27323886, 2016). "VDR has been demonstrated to behave as an antagonist to Smad3 and prevent liver fibrosis in stellate cells." (PMID 27456065, 2016). "In summary, hepcidin suppresses liver fibrosis by impeding TGFβ1-induced Smad3 phosphorylation in HSCs, which depends on Akt activated by a deficiency of ferroportin." (PMID 28004654, 2016). "The role of Smad-2 in liver fibrosis is less well characterized but in comparison with Smad-3 seems to regulate a distinct set of target genes." (PMID 27239252, 2016). "Vitamin D receptor (VDR) ligands can decrease liver fibrosis by redirecting VDR to SMAD3 sites on the DNA, thereby reducing SMAD3 occupancy." (PMID 28933415, 2016). "The results of our research provide further evidence that ghrelin alleviates liver fibrosis through modulation of the TGF-β1/Smad3 signaling pathway and autophagy inhibition in both CCl4- and BDL-induced fibrosis mouse models." (PMID 26378522, 2015). "In this study, we provided evidence that acylated ghrelin exerts antifibrotic effects against liver fibrosis via regulation of the TGF-β1/Smad3 signaling pathway." (PMID 26378522, 2015). "Our results demonstrated that ghrelin attenuates liver fibrosis via inhibition of the TGF-β1/Smad3 and NF-κB signaling pathways, as well as autophagy suppression." (PMID 26378522, 2015). "In conclusion, miR-29b was downregulated in liver fibrosis and was negatively regulated by Smad3 in vivo and in HSC cells." (PMID 25356754, 2015). "We found that ghrelin treatment ameliorated CCl4- and BDL-induced liver fibrosis via inhibition of the TGFβ1/Smad3 and NF-κB pathways, as well as autophagy suppression." (PMID 26378522, 2015). "It was recently shown that the expression of the phosphorylated Smad2 and Smad3 proteins was higher in samples of CCl4-induced liver fibrosis, compared with that in the controls." (PMID 25435153, 2015). "APE treatment (5.2 g/kg) significantly decreased Smad2 and Smad3 phosphorylation in liver tissue of rats with hepatic fibrosis (P<0.05)." (PMID 25373883, 2015).
liver fibrosis (continued). "After four weeks of exposure to CCl4, liver fibrosis in the Smad3 WT mice was more severe than in the Smad3 KO mice." (PMID 24304543, 2013). "Since proteins related to the antioxidant system were more highly expressed in Smad3 KO mice than in the Smad3 WT mice after CCl4 treatment, their presence presumably provided a significant level of protection against hepatic fibrosis." (PMID 24304543, 2013). "TGF-β/Smad3 signal pathway plays an essential role in the development of hepatic fibrosis, the blocking of which can prevent and treat hepatic fibrosis." (PMID 24693382, 2013). "The functional importance of TGF-beta/Smad signaling in liver fibrosis has been demonstrated by the finding that disruption of Smad3 protects against dimethylnitrosamine-induced hepatic fibrosis." (PMID 22363627, 2012). "Targeted disruption of Smad3 has been found to confer resistance to the development of dimethylnitrosamine-induced hepatic fibrosis in mice." (PMID 22978413, 2012). "Consistently, Smad3−/− mice, which lack the Smad3 signaling molecule downstream of TGF-β1, are much less susceptible to liver fibrosis than wild type mice." (PMID 22973518, 2012). "In addition, studies using resveratrol, gallic acid, or ferulic acid showed inhibition by reducing inflammation and liver fibrosis through the TGF‐β/Smad3 signaling pathway in mice induced with CCL4 signaling." (PMID 41322110, 2025). "This is because SMAD3 can bind directly to DNA sequences that regulate the expression of multiple collagen genes and fibrosis markers, thereby directing the progression of liver fibrosis." (PMID 39937012, 2025). "Taken together, GSH could improve the engraftment efficiency of ADSCs in liver fibrosis by targeting TGFβ1/SMAD3/NOX4 signaling pathway, which provides a new theoretical basis for GSH enhancing ADSC engraftment efficiency in liver diseases." (PMID 40060764, 2025). "For example, total flavonoids from Scabiosa comosa (TF-SC) selectively inhibit TGF-β1–induced Smad3 phosphorylation by blocking the TβRI–Smad3 interaction, thereby attenuating CCl4-induced liver fibrosis and identifying TF-SC as a potential TGF-β1/Smad3 pathway inhibitor." (PMID 41293253, 2025). "Therefore, we verified the mRNA expression levels of the TGF-β/Smad2/SMAD3 pathway, liver fibrosis, and bile acid metabolism genes." (PMID 40453659, 2025). "The TGF-β1/Smad3 signaling pathway plays a central role in the progression of liver fibrosis." (PMID 41228535, 2025). "Mechanistic studies have revealed that SIRT6 inhibits TGF-β-induced activation of hepatic stellate cells by deacetylating specific sites (K333 and K378) on Smad3, resulting in the downregulation of liver fibrosis-related genes and the inhibition of fibrosis progression." (PMID 38294557, 2024). "The TGF-β1/Smad3-signaling pathway plays a crucial role in liver fibrosis progression." (PMID 38408944, 2024). "This demonstrated that the administration of resveratrol in addition to repeated phenobarbital CCl4 in this rat liver fibrosis model could inhibit SMAD3 mRNA expression, which is a key factor for the TGF-β signal." (PMID 39055873, 2024). "Smad2/Smad3, a downstream factor of Smad signaling, is considered a key regulator of TGF-β signaling in tissue fibrogenesis, and more importantly, Smad7 is a potential major transcriptional repressor of HSC activation and liver fibrosis in vitro and in vivo, regulating Smad2/Smad3 phosphorylation." (PMID 37056286, 2023). "Within our established model of naturally aging 43 W mice, the expression of TGF-β saw significant elevation, mirrored by an upsurge in the downstream gene SMAD3′s expression—an alignment with elevated SMAD3 expression observed in IGFBPrP1-induced liver fibrosis." (PMID 38132319, 2023). "It has recently been suggested that blockers of the TGF-β/Smad3 signaling pathway could inhibit liver fibrosis in several fibrotic animal models." (PMID 37275763, 2023).
liver fibrosis (continued). "However, LEFTY2 alleviates hepatic stellate cell activation and liver fibrosis by inhibiting the TGF-β1/Smad3 pathway." (PMID 36769200, 2023). "A previous investigation suggested that inhibition of the TGF-β1/Smad3 signal transduction cascade could ameliorate liver fibrosis by suppressing autophagy." (PMID 37465345, 2023). "Therefore, one way to prevent HSC activation and reduce hepatic fibrosis is to inhibit activated HSCs by stopping the TGF-β/Smad3 signaling pathway, which is considered a potential therapeutic target." (PMID 36544529, 2022). "The results of our study suggest that IL-37-induced AMPK activation through its interaction with SMAD3 results in promotion of the polarization of macrophages to the M2 phenotype and ultimately to the reduction of liver egg granuloma and hepatic fibrosis formation in schistosomiasis." (PMID 36002836, 2022). "Moreover, we also know that expression of many fibroblast genes (collagen) and markers such as α-SMA depends on Smad3, and Smad3 directly binds to DNA sequences that regulate these target genes, thereby regulating the process of liver fibrosis." (PMID 35572578, 2022). "This phenomenon is consistent with the results in renal and liver fibrosis, and it is suggested that Smad3 protein may be involved in the progression of intestinal fibrosis." (PMID 36474625, 2022). "Our current results confirmed that apigenin could ameliorate liver fibrosis by inhibiting autophagy via the TGF-β1/Smad3 and p38/PPARα pathways." (PMID 33574836, 2021). "Researchers have demonstrated that the activation of p38 could increase the Smad3 phosphorylation in hepatic fibrosis." (PMID 33995055, 2021). "Furthermore, overexpression of miR-34 ameliorates the onset and progression of liver fibrosis by regulating the TGF-β1/mothers against decapentaplegic homolog 3 (Smad3) pathway in HSCs." (PMID 34360904, 2021). "The activation of the TGF-β1/Smad3 signaling pathway plays an important role in liver fibrosis." (PMID 33574836, 2021). "It has been shown that the flavonoid-rich aqueous extract of SCST can attenuate liver fibrosis by selectively inhibiting Smad3 phosphorylation to downregulate the transcription of fibrotic genes in a rat model of CCl4-induced hepatic fibrosis or in TGF-β1-activated HSCs." (PMID 33510287, 2021). "Here, we hypothesize that IL-37 not only suppresses liver inflammation but also modulates liver fibrosis by the interaction with Smad3." (PMID 33746950, 2021). "Moreover, TGF-β signaling induces liver fibrosis through the sequential activation of downstream mediators including Smad2 and Smad3." (PMID 34772443, 2021). "Next, we investigated whether Smad3 mediates the inhibitory effects of saracatinib on liver fibrosis." (PMID 32120837, 2020). "TGF-β/Smad signaling pathway causes liver fibrosis by hyper activation of TGF-β, Smad-3 and Col1-α." (PMID 32917140, 2020). "Smad3 appeared to be a key element responsible for fibrosis in hepatic fibrosis." (PMID 32660551, 2020). "To investigate the underlying mechanism of the effect of hFSSC secretome on liver fibrosis, we performed the Western blot and RT-qPCR to analyze the expression of TGF-β1, Smad2, Smad3, Smad7, and Collagen I in HSCs, as it is one of the major effector cells in liver fibrosis." (PMID 32883340, 2020). "The protective effect of Src inhibition against liver fibrosis was associated with the attenuation of TGF-β-induced phospho-Smad3 expression, but not with the attenuation of STAT3 phosphorylation." (PMID 32120837, 2020). "Regarding the pivotal role of the TGF-β1/SMAD3 signaling pathway in activated HSCs, it seems that inhibition of this pathway could be beneficial in treatment of liver fibrosis." (PMID 33041786, 2020). "In the context of hepatic fibrosis, Smad3 is known as a pro-fibrotic transcription factor." (PMID 33396939, 2020).